IL1A (interleukin 1 alpha)
Diseases named in the same sentence as IL1A in open-access papers (continued):
Sharing a sentence is not in itself a finding about the gene and the disease.
fibrosis (7 papers, 2015 to 2025). the formation of excess fibrous connective tissue in an organ or tissue in a reparative or reactive process. "We found that the stimulation of AIM2 led to IL-1α, IFN-α and TGF-β release from fibrosis-associated circulating cells from PC patients." (PMID 35844548, 2022). "In addition, our previous work focused on plasma biomarkers, identified high levels of IL-1α and TGF-β in PC patients with fibrosis." (PMID 35844548, 2022). "Melatonin supplementation, however, reduced cardiac fibrosis and significantly decreased the expression of IL-1α and IL-6 in WT and NLRP3−/− mice, with non-significant decline of TNFα." (PMID 34439517, 2021).
heart failure (7 papers, 2017 to 2024). Inability of the heart to pump blood at an adequate rate to meet tissue metabolic requirements. "Up-regulation of HACE1 enhanced cell viability and promoted calcien-AM/CoCl2 levels (p < 0.05), reduced LDH activity and IL-1α levels (p < 0.05), and decreased PI-positive cells and iron concentration (p < 0.05) in the in vitro heart failure model." (PMID 38070140, 2023). "Preclinical research and clinical trials validated the role of IL-1α in the initiation of post-MI inflammation and the role of IL-1β in adverse cardiac remodeling and heart failure." (PMID 33488934, 2020). "So far, it has been found that inflammatory cytokines associated with the heart failure mechanism include TNF-α, IL-6, IL-8, IL-10, IL-1α, IL-1β, IL-2, TGF-β, and IFN-γ." (PMID 31275453, 2019). "This is attributed to the release of various cytokines, such as IL-1α, IL-1β, IL-6, and TNF-α, which negatively affect myocardial healing and contribute to the development of heart failure." (PMID 38667586, 2024).
Hypertension (7 papers, 2018 to 2025). The presence of chronic increased pressure in the systemic arterial system. "Recent work using the Tg26 mouse model of HIV shows CD4+ T cells expressing viral proteins can drive hypertension through IL-1α and NOX1 pathways." (PMID 41333751, 2025).
intervertebral disc degeneration (7 papers, 2014 to 2024). "A previous study verified that in degenerative and herniated intervertebral discs, the expression levels of IL-1α and IL-1β were correlated with the grade of intervertebral disc degeneration or the extent of intervertebral disc herniation." (PMID 30008976, 2018).
keratoconus (7 papers, 2008 to 2025). A degenerative, structural disorder of the eye, characterized by a cone-shaped protrusion of the cornea. "Since rs2071376 was not linked with the IL1B SNPs, rs1143627 and rs16944, in the Japanese and Korean populations, the possibility that IL1A SNP rs2071376 is primarily associated with the development of keratoconus is low." (PMID 23592922, 2013). "The previous study showed that only the heterozygous genotype of IL1A SNP rs2071376 was associated with keratoconus in the Korean population, whereas the allele frequencies were not significantly different between the patients and the controls." (PMID 23592922, 2013). "rs2071376 located in intron 6 of IL1A showed significant association in patients with keratoconus." (PMID 26063326, 2015). "Polymorphisms in the interleukin 1 alpha (IL1A) and IL1B gene regions were previously associated with keratoconus in a Korean population." (PMID 23592922, 2013). "The *C/*A genotype of rs2071376 in IL1A intron 6 was significantly different between the keratoconus patients and control subjects (p=0.034, OR=0.59, 95% CI 0.32<1.11)." (PMID 19043479, 2008). "Previous studies indicated that corneal fibroblasts from keratoconus patients express about three times more IL1A mRNA than those from a normal cornea." (PMID 19043479, 2008). "For rs2071376 in IL1A, the AA genotype had a 1.76-fold increased risk of keratoconus, but it was not significant." (PMID 23592922, 2013). "In the present study, we investigated whether the IL1A and IL1B polymorphisms are associated with keratoconus in a Japanese population." (PMID 23592922, 2013). "The goal of this study was to elucidate whether polymorphisms in IL1A, IL1B, and IL1RN are associated with keratoconus in Korean patients." (PMID 19043479, 2008). "We investigated the association between IL1A (rs1800587, rs2071376, and rs17561), IL1B (rs1143627, rs16944, rs1143634, and rs1143633), and IL1RN (rs419598, rs423904, rs424078, and rs315952, variable number tandem repeat [VNTR]) polymorphisms in 100 unrelated Korean keratoconus patients." (PMID 19043479, 2008). "Genotype frequencies of IL1A and IL1B in keratoconus patients." (PMID 19043479, 2008). "In conclusion, the present study suggests that two SNPs in IL1B predict keratoconus predisposition in unrelated Korean patients, although further research is necessary to elucidate the relationship between the expression levels of IL1α, IL1β, and IL1Ra and SNPs of IL1B in keratoconus patients." (PMID 19043479, 2008).
kidney damage (7 papers, 2020 to 2025). "Previous reports have established that IL-1α can act as a proinflammatory signal for kidney damage, where as Eotaxin and MIP-1α (CCL3) are potent chemokines that contribute to the recruitment of immune cells and promote AKI." (PMID 41347022, 2025). "Importantly, IL-1α knockout mice were largely protected against oxalate- or adenine-induced kidney damage, which stresses the pathophysiological role of IL-1α in CKD." (PMID 40486517, 2025). "The levels of IL-11 increase.Inhibition of IL-18 can significantly prevent kidney damage.CCL5 and IL-1α slightly increase.Inhibition of TNF-α cannot significantly reduce kidney damage.NLRP3 pathway is the key pathogenesis of inflammation." (PMID 34149721, 2021). "The levels of IL-11 do not increase.Inhibition of IL-18 cannot significantly prevent kidney damage.CCL5 and IL-1α significantly increase.Inhibition of TNF-α can significantly reduce kidney damage.NLRP3 pathway is less important." (PMID 34149721, 2021).
non-small cell lung carcinoma (7 papers, 2006 to 2024). A group of at least three distinct histological types of lung cancer, including non-small cell squamous cell carcinoma, adenocarcinoma, and large cell carcinoma. "In addition, IL-1α produced by TA-pDCs was found to be responsible for promoting cell proliferation and angiogenesis in non-small cell lung cancer (NSCLC)." (PMID 39020402, 2024).
oral cancer (7 papers, 2012 to 2025). "Background/Objectives: Interleukin-1 alpha (IL-1α) has been linked to tumor progression in various cancer types; however, its role in oral cancer pathogenesis remains largely unexplored." (PMID 40940885, 2025). "Although recent studies have reported associations between IL-1α and the pathophysiology of various carcinomas, its role in oral cancer pathogenesis remains largely unexplored." (PMID 40940885, 2025). "For example, IL-1α secreted from oral carcinoma cells (OSCC) was shown to induce chemokine (C–C motif) ligand 7 (CCL7) release from oral CAF, which in turn promoted OSCC invasion." (PMID 41392310, 2025). "In most cases, pro-inflammatory cytokines (IFN-γ, IL-2, IL-1α, IL-1β, TNF-α, IL-17, and IL-8), anti-inflammatory cytokines (IL-4 and IL-10), and pro-/anti-inflammatory cytokines (IL-6 and TGF-β) are unbalanced in oral cancer, resulting in an immunosuppressive environment." (PMID 37686542, 2023).
osteomyelitis (7 papers, 2019 to 2024). An acute or chronic inflammation of the bone and its structures due to infection with pyogenic bacteria. "An association between a (-889) polymorphism of the promoter region of IL-1α and susceptibility to juvenile rheumatoid arthritis and to osteomyelitis was also reported." (PMID 36319725, 2022). "To determine the contribution of MyD88 and IL-1R signaling towards antibacterial immune responses during S. aureus osteomyelitis, we infected mice globally deficient in MyD88, IL-1R, IL-1α, and IL-1β and measured bacterial burdens and morbidity." (PMID 30978245, 2019). "We have previously found that variants in the genes of IL-1α, MMP1, TLR4 receptor, endothelial nitric oxide synthase (NOS3), Bax and tPA also contribute to the risk of developing osteomyelitis with prevalences of between 3.8% and 65.3%." (PMID 31647805, 2019). "In this respect, several preclinical and clinical observations indicate that osteomyelitis is accompanied by alterations in the local and (sometimes) systemic levels of both pro-inflammatory (e.g., IL-6, IL-1α, TNF-α, IL-1β) and anti-inflammatory (e.g., TGF-β1) cytokines." (PMID 36483565, 2022).
parasite infection (7 papers, 2015 to 2025). "Systemically, IL-1α deficiency attenuated weight loss and hypothermia but had minor effects on parasitemia control." (PMID 31110285, 2019). "Systemically, IL-1α promoted hypothermia and weight loss, but played a minor role in the control of parasitemia." (PMID 31110285, 2019). "At 8 d PI in baso IL-4/IL-13 (−) mice, FITC-dextran levels were positively correlated with parasitemia, plasma IL-1α, IFN-γ and IL-9, while bacterial 16S copies were positively correlated with plasma IFN-γ and IL-12p40." (PMID 38780542, 2024). "These mice showed similar parasitemias until day 7 p.i., but higher levels were found in Il1a−/− mice compared to C57BL/6 mice at days 8 and 9 p.i.." (PMID 31110285, 2019). "Similarly, during infection with the parasite Toxoplasma gondii, microglia produce the alarmin IL-1α, which is required to initiate immune cell infiltration and control parasite infection." (PMID 40522474, 2025). "Eotaxin was positively correlated with NE and plasma RANTES (CCL5), IL-1α, and IL-2, and strongly negatively correlated with MPO, Mcpt1, parasitemia, plasma IL-4, ileal MCs, and FITC-dextran." (PMID 38780542, 2024). "We assessed the serum levels of six cytokines (i.e. IL-1α, IL-1β, IFNγ, CXCL10, CXCL9, TNFα) at the first peak of parasitemia of both 1/148 and IL3000 infections." (PMID 35787830, 2022). "Serum concentration of IL-1α, IL-1β, IFNγ, CXCL10, CXCL9, TNFα in non-infected mice and mice infected with either 1/148 or IL3000, at the first peak of parasitemia (Mean ± SEM; N=3–4)." (PMID 35787830, 2022).
prion disease (7 papers, 2019 to 2021). A transmissible disease that is caused by a protein that is able to induce abnormal folding of normal cellular proteins, leading to characteristic spongiform brain changes, which are associated with neuronal loss without an inflammatory response. "Unexpectedly, elimination of three microglia-derived factors TNF-α, IL-1α and C1qa, which were thought to drive polarization of astrocytes into a neurotoxic state, accelerated the progression of prion diseases." (PMID 33980286, 2021). "In prion diseases, the expression levels of Il1a, Tnfa and C1q were upregulated, yet astrocytes did not exhibit well-defined A1 phenotype, suggesting that the relationship between microglia and astrocytes is complex." (PMID 33546775, 2021). "Whereas CNS prion disease was unaltered in mice deficient in TNF-α or C1q, the combined deficiency in TNF-α, IL-1α and C1q was shown to accelerate the disease." (PMID 33023255, 2020). "Of note, TNF-α, IL-1α and C1qa are upregulated in mouse models of prion disease and TNF-α and IL-1α in human CJD, which would make polarization of astrocytes towards A1 very likely in prion diseases." (PMID 31118110, 2019). "Although the deposition of misfolded PrPSc was unchanged, we found that knockout of TNF-α, IL-1α and C1qa with the abolishment of C3+-astrocyte formation let to a significant acceleration of the prion disease course." (PMID 31118110, 2019). "Surprisingly, abolishment of C3+-astrocyte formation by knocking out TNF-α, IL-1α and C1qa accelerated the prion disease course." (PMID 31118110, 2019). "We then investigated the impact of these astrocytes on prion disease pathophysiology by prion infecting mice with a knockout of the three cytokines TNF-α, IL-1α and C1qa, which are unable to develop A1-astrocytes upon stimulation." (PMID 31118110, 2019). "This suggests that in the steady state, factors independent of microglial-derived TNF-α, IL-1α and C1q are required for the activation of astrocytes in the prion disease-affected brain." (PMID 33023255, 2020). "Recently, the influence of microglia-induced A1-reactive astrocytes during prion disease was assessed by infecting triple knockout mice lacking Tnf, IL-1a, and C1qa with prions." (PMID 32381108, 2020). "In contrast, the impact of knockout of IL-1α or all three cytokines in prion disease pathophysiology has never been studied before." (PMID 31118110, 2019). "Therefore, it would be interesting to determine, if C3aR is altered in prion diseases and could pose a more suitable target than the cytokine triad TNF-α, IL-1α and C1qa." (PMID 31118110, 2019). "To investigate their impact on prion disease pathophysiology and to evaluate their potential therapeutic targeting, we infected TNF-α, IL-1α, and C1qa Triple-KO mice (TKO-mice), which do not transit astrocytes into A1, with prions." (PMID 31118110, 2019). "Therefore, we intra-cerebrally infected Triple-KO mice (TKO) lacking expression of TNF-α, IL-1α and C1qa (which fail to develop A1 reactive astrocytes following inflammatory insult) with RML-prions and determined pathophysiology of prion disease progression in comparison to infected WT-mice (WT)." (PMID 31118110, 2019).
respiratory failure (7 papers, 2021 to 2025). The significant impairment of gas exchange within the lungs resulting in hypoxia, hypercarbia, or both, to the extent that organ tissue perfusion is severely compromised. "It is reported that the excessive production of inflammatory cytokines, such as TNF-α and IL-1α, induces disseminated intravascular coagulation, respiratory failure, and multiorgan failure." (PMID 35107382, 2022).
skin cancer (7 papers, 2012 to 2025). "Long-term exposure to UV irradiation and toxic chemicals is associated with chronic inflammation that contributes to skin cancer development with interleukin-1 alpha (IL-1α), constitutively produced by keratinocytes, playing a pivotal role in skin inflammation." (PMID 22792469, 2012). "IL1A inhibits papilloma-to-carcinoma conversion in skin cancer and impedes cancer cell growth in vitro across multiple cancer types." (PMID 40612864, 2025). "Activation of K-Ras, a potent oncogene that drives the development of multiple cancers, in transformed skin cells resulted in production of IL-1α, which signals in an autocrine manner through IL-1R/MyD88/NF-κB pathway to synergize with K-Ras for the oncogenic progression of skin cancer." (PMID 31051015, 2016). "Fisetin has significant effect on production of free fatty acids, tumor incidence, IL‐1α, TNF‐α, and antioxidant enzymes (glutathione and catalase contents) in ultravoilet‐induced skin cancer rats." (PMID 33473265, 2021). "Regarding the source of IL-1 cytokine in skin cancer, it has been shown that UV challenge or TPA stimulation leads to production of IL-1α by keratinocytes." (PMID 31051015, 2016).
vasculitis (7 papers, 2013 to 2023). "Together with IL1-β, the IL-1α plays an important role in the development of KD vasculitis." (PMID 34362028, 2021). "Thus, IL-1A, IL-1B, and IL1RN are considered attractive candidate genes for vasculitis." (PMID 31093510, 2019).
brain inflammation (6 papers, 2011 to 2023). "Notably, in contrast to the brain inflammation model investigated by Horai and colleagues, we observed a normal postoperative upregulation of either IL-1α or IL-1β in the ME of IL-1β- or IL-1α-deficient mice, respectively." (PMID 31332247, 2019). "Only LPS-treated mice showed elevated granulocyte levels and IL-1α expressing cells in the ipsilateral hemisphere after hypothermia and MCAo (not shown), indicating that peripheral LPS initiates brain inflammation even if the ischaemic brain damage is reduced." (PMID 22114895, 2011).
chronic kidney disease (6 papers, 2020 to 2025). Impairment of the renal function secondary to chronic kidney damage persisting for three or more months. "Interestingly, both cytokines (IL1A and IL-6) have been implicated as key factors linking malnutrition, accelerated atherogenesis, and excessive morbidity and mortality in end-stage renal disease (ESRD) patients in hemodialysis." (PMID 31924810, 2020). "Interestingly, recent studies have shown that IL-1α functions as a proinflammatory mediator and has been proposed as a therapeutic target for the treatment of chronic kidney disease." (PMID 37228128, 2023). "Interestingly, IL-1A has recently been proposed as a therapeutic target for the treatment of chronic kidney disease." (PMID 37228128, 2023).
chronic lung disease (6 papers, 2018 to 2021). According to the definitions of the American and British Thoracic Societies, including pulmonary functional tests, X-rays, and CT scans for items such as fibrosis, bronchiectasis, bullae, emphysema, nodular or lymphomatous abnormalities. "We analyzed the expression of selected genes associated with AM plasticity (Ccl22, Ccl17, Mmp12, and Arg1) and inflammation in chronic lung diseases (Il1a and Il1b)." (PMID 34764283, 2021). "Thus, we propose that IL-36R blockade in patients with chronic lung disease prone to microbial exacerbations will alleviate symptoms while preserving sufficient innate immune signaling mediated by IL-1α and IL-1β to conserve host defense." (PMID 33558616, 2021). "IL-1α has been repeatedly reported as involved in chronic lung diseases." (PMID 34944747, 2021). "The involvement of IL-1α in chronic lung diseases has been repeatedly reported." (PMID 29675024, 2018). "Inflammasomes are multi-protein complexes that act as platforms for cleavage (i.e. activation/maturation) of pro-cytokines of the IL-1 family (e.g. IL-1α, IL-1β, IL-18), which are prominent inflammatory cytokines in COPD and other chronic lung diseases." (PMID 34022905, 2021).
cystic fibrosis (6 papers, 2012 to 2023). Autosomal recessive disorder caused by pathogenic variants in the CFTR gene (cystic fibrosis transmembrane conductance regulator), which encodes a chloride and bicarbonate channel expressed in epithelial cells, and follow the diagnosis criteria. "In cystic fibrosis, rhinovirus- and hypoxia-induced epithelial necrosis causes IL-1α release and subsequent IL‐8 expression, which may promote neutrophilic inflammation." (PMID 36168003, 2023). "IL-1α fragments, similar to those produced by GrB, were found in BAL in human airway inflammatory diseases, as COPD, cystic fibrosis and bronchiectasis, while GrB activity on IL-1α was demonstrated in vivo in GrB knockout mice, strongly suggesting that this activity also exists in vivo." (PMID 33262766, 2020). "This was found to be important in persistent inflammatory lung conditions such as cystic fibrosis, as patient bronchoalveolar lavage fluids could process IL-1α to a mature form." (PMID 33391283, 2020). "HMGB1 like IL-1α is found in CF sputa, whereas S100A9 is a part of Calprotectin, a complex described as the Cystic Fibrosis protein in 1973." (PMID 26793709, 2015).